OR6S1 (olfactory receptor family 6 subfamily S member 1)
Description:
Odorant receptor.
Synonyms: OR6S1Q; OR14-37
Tractability: Antibody: UniProt places it where antibodies can reach, with medium confidence; UniProt predicts a signal peptide or a membrane-spanning region; its Gene Ontology location is reachable by antibodies, with medium confidence.
Gene: Protein-coding gene on chromosome 14 (20,640,696 to 20,641,691, reverse strand). Ensembl gene ENSG00000181803.
Subcellular location: Cell membrane
Pathways (Reactome):
Sensory Perception: Expression and translocation of olfactory receptors
Gene Ontology:
Molecular function: olfactory receptor activity; G protein-coupled receptor activity
Biological process: detection of chemical stimulus involved in sensory perception of smell; G protein-coupled receptor signaling pathway
Cellular component: plasma membrane; membrane
Genetic constraint (gnomAD): Loss-of-function variants: 0 observed, 0.29 expected, observed/expected ratio (o/e) 0, 90% interval 0 to 1.87. That is too few expected variants to judge how well the gene tolerates losing a copy. Missense variants: 443 observed, 420 expected, observed/expected ratio (o/e) 1.05, 90% interval 0.98 to 1.14. Synonymous variants: 181 observed, 175.16 expected, observed/expected ratio (o/e) 1.03, 90% interval 0.92 to 1.17.
Homologues: Orthologues: chimpanzee OR6S1 (98% identical), pig OR6S1 (85% identical), guinea pig OR6S1 (84% identical), mouse Or6s1 (83% identical), rabbit OR6S1 (83% identical), rat Or6s1 (83% identical). Paralogues in human: OR6J1 (49% identical), OR6M1 (49% identical), OR6T1 (47% identical), OR6F1 (46% identical), OR6V1 (44% identical), OR6X1 (44% identical), OR6C4 (43% identical), OR6C75 (43% identical), OR6C76 (43% identical), OR6C2 (42% identical), OR2AP1 (42% identical), OR6C6 (41% identical), and 6 more.
Diseases named in the same sentence as OR6S1 in open-access papers:
OR6S1 is named in the same sentence as 1 disease in open-access papers, as found by Europe PMC text mining. Sharing a sentence is not in itself a finding about the gene and the disease.
OR6S1 shares sentences with these, for which no sentence is quoted: copy number variation (1 paper).